SEMA3E (semaphorin 3E)
Diseases named in the same sentence as SEMA3E in open-access papers (continued):
Sharing a sentence is not in itself a finding about the gene and the disease.
asthma (continued). "Semaphorin 3e’s involvement in the airway’s pathobiology, such as asthma, has been reported." (PMID 41229427, 2025). "Therefore, we aimed to investigate the role of Sema3E in a mouse model of severe asthma that exhibits a mix of granulocytic inflammation with neutrophils dominance and compared the results with those from the type-2 high eosinophilic asthma model." (PMID 40512736, 2025). "Concurrently, Sema3E KO mice that were subjected to the type-2 low asthma model demonstrated an elevated presence of pulmonary neutrophils, dendritic cells, CD4 T cells, as well as increased levels of IL-17, TNF, IL-1β, CXCL-8, and MCP-1/CCL2 in comparison to their WT counterparts." (PMID 40512736, 2025). "Furthermore, tissue resistance (G) demonstrated a significant increase in the Sema3E KO type-2 high asthma model that peaked at the 12 mg/ml (p < 0.001) and dose 50 mg/ml methacholine dose (p < 0.05) compared with the WT counterpart." (PMID 40512736, 2025). "Notably, Semaphorin3E (Sema3E) has emerged as a significant regulatory molecule in asthma, influencing both the immune response and airway remodeling." (PMID 39213301, 2024). "In asthma models sensitized by other substances (such as ovalbumin and diesel exhaust), whether Sema3E can effectively reduce airway responsiveness is unknown." (PMID 38111650, 2023). "Moreover, their recent study clearly demonstrated a suppressed Sema3E expression in human severe asthma using bronchial biopsy and lung tissue histology speciments." (PMID 30134791, 2018). "However, the potential contribution of Sema3E in chronic features of asthma has remained to be addressed." (PMID 29228740, 2017). "However, it is not still clear that whether allergen exposure primarily induces downregulation of Sema3E; genetic defect of Sema3E leads to a heighten asthma pathology; or a combination of both possibilities are involved." (PMID 29228740, 2017). "Sema3E KO mice displayed increased AHR and sensitivity to methacholine, especially in the type-2 low asthma model." (PMID 40512736, 2025). "Our findings reveal that Sema3E plays a pivotal role in regulating airway hyperresponsiveness (AHR), inflammation, and tissue remodeling across different asthma phenotypes." (PMID 40512736, 2025). "In the type-2 low asthma model, we observed a higher number of neutrophils (p < 0.0001), dendritic cells (DC) (p < 0.0001), and CD4 + T cells (p < 0.05) in Sema3E KO mice compared to WT mice." (PMID 40512736, 2025). "Overall, our data showed that Sema3E is critical in modulating AHR, airway inflammation, and tissue remodelling in type 2 low and type 2 high phenotypes of asthma." (PMID 40512736, 2025). "Although the impact of Sema3E has been investigated in the acute and chronic HDM models of asthma, which represent type-2 high asthma in humans, its role in type-2 low or neutrophilic asthma using cyclic-di-GMP remains unexplored." (PMID 40512736, 2025). "The Sema3E-plexinD1 axis plays a crucial regulatory role in airway hyperresponsiveness (AHR) and other key features of asthma." (PMID 40512736, 2025). "Sema3E in lungs and vagal ganglia is related to eosinophilic inflammation and has a protective effect on OVA-induced AHR in asthma." (PMID 38111650, 2023). "We established chronic asthma model by intranasal HDM exposure for 5 consecutive weeks and then treated mice with either Sema3E or saline for another 2 weeks then re-challenged with HDM for one week." (PMID 29228740, 2017). "Given the potential of Sema3E as a therapeutic target for allergic HDM asthma, we sought to investigate the role of Sema3E in type 2-low asthma using preclinical models and to compare the effects of Sema3E deficiency in this model with those observed in the type 2-high asthma phenotype." (PMID 40512736, 2025). "Our results revealed that airway resistance (Rn) did not increase in response to Sema3E deletion compared to WT mice in the type-2 low asthma model." (PMID 40512736, 2025).
asthma (continued). "Sema3E KO and wild-type mice were exposed to c-di-GMP + HDM or HDM alone for four weeks, as outlined in the model plan, to induce mixed granulocytic with neutrophil dominance and eosinophil dominance asthma models, respectively." (PMID 40512736, 2025). "Our research has shown that the absence of Sema3E worsens asthma symptoms in acute and chronic asthma models." (PMID 39213301, 2024). "Second, we did not used gene knockout mouse for validating the effect of Sema3E on asthma AHR and airway inflammation." (PMID 38111650, 2023). "Therefore, this study aimed to observe the Sema3E levels expressed in the vagal ganglion and lung tissues in OVA-induced asthma and EB mouse models, and to investigate the possible therapeutic effects of Sema3E on asthma." (PMID 38111650, 2023). "This could be interpreted as increased hypersensitivity of the airways to the methacholine dose, rather than hyperreactivity in type-2 low asthma following Sema3E deletion." (PMID 40512736, 2025). "However, the levels of IFN-γ, IL-10, and type-2 cytokines, including IL-4, IL-5, and IL-13, were not significantly different between Sema3E KO and WT mice in the type-2 low asthma model." (PMID 40512736, 2025). "In the type-2 high asthma model, although Sema3E KO mice did not display statistically significance exaggerated airway resistance (Rn) compared to WT mice, there is a higher trend in airway resistance and hyperreactivity in Sema3E KO compared to WT counterpart." (PMID 40512736, 2025). "However, the role of Sema3E in type 2 low asthma has not been investigated." (PMID 40512736, 2025). "In type-2 high asthma, the number of inflammatory cells, including neutrophils, cDC, CD4 T cells, macrophages, and B cells did not change in Sema3E KO mice compared to WT counterparts." (PMID 40512736, 2025). "However, in response to Sema3E deletion, the total and HDM specific serum IgG1 and IgE levels did not change compared to WT mice in both models of asthma." (PMID 40512736, 2025).
melanoma (8 papers, 2011 to 2022). A malignant, usually aggressive tumor composed of atypical, neoplastic melanocytes. "In contrast, Sema3E levels were found to be inversely associated with tumor progression in melanoma and in another study of gastric cancer." (PMID 27911862, 2016). "These contrasting results indicate that great attention and new studies are necessary before considering Sema3E or plexinD1 as possible target for melanoma treatment." (PMID 33858502, 2021). "Among these genes, we focused on SEMA3E, which has an expression level reported to be positively correlated with increased metastasis in ovarian, melanoma, and colon cancers." (PMID 30898102, 2019). "In particular, Sema3E and its mature isoform Sema3E-p61 regulate migration and invasion of melanoma, colon, lung, and ovarian cancer cells, and Sema3E-PlexinD1 signaling was reported to promote invasive/metastatic phenotype." (PMID 27749937, 2016). "For example, down-regulation of Sema3E in melanoma facilitates tumor angiogenesis for distant metastasis, while Sema3E overexpression in mammary adenocarcinoma promotes peri-tumor local endothelial cell migration for invasive growth and lung metastasis." (PMID 21559368, 2011). "Furthermore, while the canonical ligand of PLEXIND1 is Semaphorin 3E (Sema 3E), a study reported that in human melanoma, PLEXIND1 aided the invasive and metastatic nature of cancer and Sema 3E was not the activating ligand." (PMID 34439202, 2021). "Contrasting results were obtained regarding the role of Sema3E in melanoma." (PMID 33858502, 2021). "Contrasting results have been evidenced regarding Sema3E, showing either positive or negative effect in melanoma progression." (PMID 33858502, 2021). "In fact, SEMA3E and its receptor PLXND1 was reported to promote tumor invasiveness and metastatic spreading of melanoma in mice, and SEMA3A was found to suppress tumor growth and metastasis in melanoma." (PMID 32640719, 2020).
allergic asthma (7 papers, 2017 to 2025). A asthma with a basis in a pathological type I hypersensitivity reaction. "The deficiency of Sema3E in murine models of allergic asthma resulted in a significant infiltration of granulocytes into the pulmonary tissue, along with an amplified Th2/Th17 immune response." (PMID 40512736, 2025). "Using a mouse model of HDM-induced allergic asthma, we revealed that Sema3E-deficient (KO) mice exhibited an increased population of CD11c+ CD11b+ CD103- DCs, which consequently led to Th2/Th17 immune activation compared to wild-type mice." (PMID 39213301, 2024). "As AHR is a hallmark clinical manifestation of allergic asthma, we first assessed the effects of Sema3E gene deletion on basal and HDM-induced AHR by studying lung function parameters." (PMID 29228740, 2017). "In contrast, the intranasal administration of exogenous Sema3E reduced these pathological effects, hence underscoring the essential role of the Sema3E-plexinD1 axis in maintaining homeostasis in allergic asthma." (PMID 40512736, 2025). "In contrast, intranasal administration of recombinant Sema3E mitigated these pathological changes, highlighting the essential homeostatic function of the Sema3E-PlexinD1 signaling axis in allergic asthma." (PMID 39213301, 2024). "In light of these findings, we conclude that Sema3E is a guidance cue for recruiting lung DCs and modulates T and B cell responses in allergic asthma." (PMID 39213301, 2024). "In a mouse model of allergic asthma, exogenous Semaphorin 3E (Sema3E) treatment reduces Th17 cytokine response leading to diminished collagen deposition, airway hyperresponsiveness, and eosinophilic inflammation." (PMID 36902294, 2023). "Sema3E deficiency in mice leads to exaggerated allergic airway inflammation, remodelling, and airway hyperresponsiveness, while intranasal recombinant Sema3E treatment reduced house dust mite-induced allergic asthma." (PMID 35983029, 2022). "Intranasal exogenous Sema3E protects mice from allergic asthma by reducing eosinophilic inflammation, serum IgE, and Th2 cytokines." (PMID 35983029, 2022). "We have previously reported an essential regulatory role of Sema3E in mouse model of allergic asthma which is mediated in part through modulating DC functions in vivo." (PMID 34185781, 2021). "Since BMDC have been directly differentiated from the progenitor cells at presence of GM-CSF, the potential impact of Sema3E on development of immune cells under healthy and pathological, conditions e.g. allergic asthma, was further investigated." (PMID 34185781, 2021). "In summary, reduction of Sema3E expression in chronic mouse model of allergic asthma suggests a potential role of this mediator in this disease." (PMID 29228740, 2017). "In the present study, we demonstrated that chronic exposure to HDM markedly reduces Sema3E immunoreactivity in mouse airways suggestive of a potential protective role for this mediator against chronic deficits of allergic asthma." (PMID 29228740, 2017). "Chronic features of allergic asthma including airway hyper-responsiveness (AHR), inflammation, and remodeling were studied in Sema3E-deficient mice." (PMID 29228740, 2017). "In our recent studies, we have uncovered that Sema3E plays a crucial regulatory role in an acute model of allergic asthma." (PMID 29228740, 2017). "We also revealed that in chronic mouse model of allergic asthma genetic abrogation of Sema3E exaggerates the development of AHR, remodeling and inflammation." (PMID 29228740, 2017). "Expression of Sema3E in a chronic model of allergic asthma was assessed after exposure to house dust mite (HDM) as a clinically relevant allergen." (PMID 29228740, 2017). "Remarkable reduction of Sema3E in the chronic model of allergic asthma is similar to our previous findings on the acute model of the disease and also severe human patients." (PMID 29228740, 2017).
allergic asthma (continued). "Enhanced AHR, remodeling, and inflammation in Sema3E-deficinet mice as well as reversion of these pathological features upon Sema3E treatment provide a novel biological therapeutic approach for chronic allergic asthma in the future." (PMID 29228740, 2017). "The Sema3E-plexinD1 axis is known to regulate both neutrophils and eosinophils in allergic asthma." (PMID 40512736, 2025). "Sema3E plays a significant role in modulating DC behavior in allergic asthma." (PMID 39213301, 2024). "However, the role of Sema3E in allergic asthma (AS) and eosinophilic bronchitis (EB) is still elusive." (PMID 38111650, 2023). "In order to investigate the direct effects of Sema3E on the airway inflammation and airway reactivity of allergic asthma mouse model, mice were sensitized and challenged with OVA to establish AS mouse model, and mice were exposed intranasally to Sema3E 1 hr before intranasal challenge." (PMID 38111650, 2023). "Notably, the modulating function of Sema3E in lung DC subsets was recently reported in an allergic asthma model induced by HDM." (PMID 35983029, 2022). "Our recent studies on an acute model of the disease indicate that Sema3E could play an essential role in allergic asthma by regulating the function of neutrophils and dendritic cells." (PMID 29228740, 2017). "Collectively, these data suggest that Sema3E could play an essential inhibitory role in reversing pathological features of chronic allergic asthma." (PMID 29228740, 2017). "Our study suggests that Sema3E could be considered as a novel treatment for chronic allergic asthma via regulation of both Th2, e.g. IL-4 and IL-5, and Th17, e.g. IL-17A, associated cytokines." (PMID 29228740, 2017). "We have further addressed a canonical role for Sema3E in acute model of allergic asthma in vivo." (PMID 29228740, 2017). "In this study, we have hypothesized that Sema3E negatively regulates chronic features of allergic asthma induced by consecutive HDM exposure." (PMID 29228740, 2017). "Also, in vivo studies on mice indicate that Sema3E treatment reduces allergic asthma by reducing eosinophilic inflammation, serum IgE level, and Th2 cytokine response and is proposed as a novel treatment option for allergic asthma." (PMID 35983029, 2022). "Furthermore, we previously revealed worsened AHR parameters, such as airway resistance (Rn), tissue resistance (G), and tissue elastance (H), in allergic asthma with a global absence of Sema3E, the canonical ligand for plexinD1." (PMID 39213301, 2024).
Insulin resistance (7 papers, 2018 to 2025). Increased resistance towards insulin, that is, diminished effectiveness of insulin in reducing blood glucose levels. "The soluble form of Plexin-D1, which binds to Sema3E and inhibits its activity, markedly suppresses inflammation in adipose tissues and improves insulin resistance." (PMID 35045890, 2022). "In contrast, the overexpression of Sema3E in adipose tissues exacerbates adipose tissue inflammation and insulin resistance through enhanced accumulation of inflammatory macrophages in visceral white adipose tissues." (PMID 35045890, 2022). "The Sema3E–Plexin-D1 signaling axis promotes inflammatory macrophage infiltration into visceral white adipose tissues, leading to adipose tissue inflammation and insulin resistance." (PMID 35045890, 2022). "Inhibition of the Sema3E-PlexinD1 axis markedly reduced adipose tissue inflammation and improved insulin resistance, whereas overexpression of Sema3E in adipose tissue promoted infiltration of macrophages, adipose inflammation, and insulin resistance." (PMID 32781674, 2020).
colorectal cancer (6 papers, 2011 to 2025). A primary or metastatic malignant neoplasm that affects the colon or rectum. "PLXNDI, in conjugation with SEMA3E, enhances the Epithelial-Mesenchymal Transition by activating the PI3/Akt signaling pathway in colorectal cancer and through SEMA3E in endometrioid cancer." (PMID 38627856, 2024). "Recent studies showed that SEMA3E expression is inversely correlated with tumor prognosis in pancreatic and colorectal cancer." (PMID 28052097, 2017). "By contrast, Sema3E/Plexin-D1 signaling in colorectal cancers increases cellular invasiveness and metastasis." (PMID 21559368, 2011).
prostate carcinoma (6 papers, 2011 to 2021). A carcinoma that arises from epithelial cells of the prostate gland. "The authors reported up-regulation of Sema3C and downregulation of Sema3A and Sema3E levels after exposure to hypoxia or hypoxic mimetic agents, thus suggesting a different role of Sema3 family members in the progression of prostate cancer." (PMID 33858502, 2021). "On the contrary, genes whose loss/down-regulation was implicated in prostate cancer cell invasion, metastasis formation and worse prognosis (AR, IGF1, IGF2, TGFB3, SEMA3E) were down-regulated in NE-like versus AdenoPCa tumors." (PMID 32041153, 2020). "In prostate cancer cells, Sema3E-PlexinD1 axis was previously reported to regulate migration; however, implicated mechanisms were not elucidated." (PMID 27749937, 2016). "Similar to other tumors, in prostate cancer, Sema3E was found to be expressed at higher levels compared to normal tissue; PlexinD1 staining too was found to be higher in tumors compared to benign tissue." (PMID 27749937, 2016). "It was further observed that the cleaved form of Sema3E, Sema3E-p61, was expressed in prostate cancer cell lines." (PMID 27749937, 2016). "Sema3E-PlexinD1 signaling was recently reported to be upregulated in prostate cancer and regulate cell migration." (PMID 27749937, 2016). "For example, expression of Sema3E in prostate cancers and metastatic melanoma inhibits adhesion and motility of cancer cells." (PMID 21559368, 2011). "Indeed, here we show that p61-Sema3E signaling enhanced prostate cancer cells migration, while knocking down the endogenous Sema3E or PlexinD1 levels inhibited it." (PMID 27749937, 2016). "Yet, the molecular mechanisms by which Sema3E-PlexinD1 signaling could induce the migration of prostate cancer cells are presently unknown." (PMID 27749937, 2016). "Thus we tested whether inhibitors of intracellular signaling effectors PI3K and MAPK could interfere with Sema3E/PlexinD1 dependent upregulation of Slug levels in prostate cancer cells." (PMID 27749937, 2016). "However, we found that this mechanism is unlikely to have a role in PC3 prostate cancer cells, as they express low levels of ErbB2 and the treatment with the kinase inhibitor lapatinib didn’t seem to interfere with Sema3E/PlexinD1-mediated effects (M.R., unpublished results)." (PMID 27749937, 2016). "In prostate cancer cells, HRE sequences have been found in the promoter of Sema3A, Sema3B, Sema3C, Sema3E, and Sema3F genes, but not in Sema3D." (PMID 33858502, 2021).